SMPD2 (sphingomyelin phosphodiesterase 2)
Description:
Catalyzes, at least in vitro, the hydrolysis of sphingomyelin to form ceramide and phosphocholine. Also hydrolyzes 1-O-alkyl-2-lyso-sn-glycero-3-phosphocholine (lyso-platelet-activating factor) in vivo. Also acts on 1-acyl-2-lyso-sn-glycero-3-phosphocholine (lyso-PC) and sphingosylphosphocholine.
Synonyms: nSMase; nSMase1; ISC1
Tractability: Small molecule: a structure with a bound ligand is known; it belongs to a druggable protein family. Antibody: its Gene Ontology location is reachable by antibodies, with high confidence; UniProt places it where antibodies can reach, with medium confidence; UniProt predicts a signal peptide or a membrane-spanning region; the Human Protein Atlas places it where antibodies can reach. PROTAC: ubiquitination databases record sites on it; its protein half-life has been measured; a small molecule that binds it is known.
Target class: Enzyme; Phosphodiesterase
Gene: Protein-coding gene on chromosome 6 (109,440,678 to 109,443,920, forward strand). Ensembl gene ENSG00000135587.
Subcellular location: Cell membrane
Subcellular location (Human Protein Atlas): Plasma membrane; Vesicles; Cell Junctions
Pathways (Reactome):
Signal Transduction: Ceramide signalling; TNFR1-mediated ceramide production
Metabolism: Glycosphingolipid catabolism
Gene Ontology:
Molecular function: phosphoric diester hydrolase activity; protein binding; sphingomyelin phosphodiesterase activity; catalytic activity
Biological process: sphingomyelin catabolic process; ceramide biosynthetic process; sphingolipid catabolic process; sphingomyelin metabolic process; ceramide metabolic process; intracellular signal transduction; response to mechanical stimulus; sphingolipid metabolic process
Cellular component: caveola; cell periphery; endoplasmic reticulum; plasma membrane
Genetic constraint (gnomAD): Loss-of-function variants: 36 observed, 45.47 expected, observed/expected ratio (o/e) 0.79, 90% interval 0.61 to 1.05. The upper end of that interval is the gene's LOEUF score, 1.05, which puts it in group 4 of 6, group 1 being the genes least tolerant of losing a copy. Missense variants: 520 observed, 553.22 expected, observed/expected ratio (o/e) 0.94, 90% interval 0.87 to 1.01. Synonymous variants: 201 observed, 220.71 expected, observed/expected ratio (o/e) 0.91, 90% interval 0.81 to 1.02.
Homologues: Orthologues: chimpanzee SMPD2 (99% identical), macaque SMPD2 (96% identical), dog SMPD2 (86% identical), pig SMPD2 (84% identical), rabbit SMPD2 (84% identical), rat Smpd2 (79% identical), guinea pig SMPD2 (78% identical), mouse Smpd2 (75% identical), tropical clawed frog smpd2 (40% identical), zebrafish smpd2a (40% identical), zebrafish smpd2b (40% identical), Caenorhabditis elegans T27F6.6 (31% identical), and 1 more.
Diseases named in the same sentence as SMPD2 in open-access papers:
SMPD2 is named in the same sentence as 68 diseases in open-access papers, as found by Europe PMC text mining. Sharing a sentence is not in itself a finding about the gene and the disease. The quoted sentences say what the papers report.
breast carcinoma (14 papers, 2007 to 2025). "could show that inhibition of SMPD2 and SMPD3 gene expression as well as inhibition of nSMase activity through GW4869 enhanced lEV release from a breast cancer cell line." (PMID 34951654, 2021). "We found that SMPD2, SMPD4, and SMPD5 were significantly higher in breast cancer tissue than that in paired normal breast tissue, while SGMS2 was significantly decreased in breast cancer tissue (TCGA cohort, n=112)." (PMID 29731990, 2018).
liver cancer (2 papers, 2018 to 2023). An epithelial or non-epithelial malignant neoplasm that arises from the liver. "As a result, we aimed to confirm whether inhibiting SMPD2 or CSTA enhances the sensitivity of liver cancer cells to lapatinib." (PMID 37006285, 2023).
melanoma (2 papers, 2025). A malignant, usually aggressive tumor composed of atypical, neoplastic melanocytes. "Flow cytometry analysis confirmed a significant reduction in ARG1+ M2-like TAMs in the Smpd2 knockdown melanoma metastases." (PMID 41321310, 2025). "To investigate whether SMPD2 promotes melanoma development by inducing M2-like TAM polarization, we conducted experiments using murine models." (PMID 41321310, 2025). "However, in immunocompetent C57BL/6J mice, Smpd2 knockdown in B16 melanoma cells significantly delayed both melanoma growth and lung metastasis." (PMID 41321310, 2025). "To explore how SMPD2 is regulated by ZDHHC13, we performed IP followed by mass spectrometry to identify potential substrates of ZDHHC13 in melanoma cells." (PMID 41321310, 2025). "We conducted an additional analysis using a human melanoma tissue array (ME551) and observed a strong inverse correlation between ZDHHC13 and SMPD2 protein expression." (PMID 41321310, 2025). "However, we observed that many ZDHHC13-interacting proteins showed significant correlation with SMPD2 and PLA2G15 expression levels in human melanoma datasets." (PMID 41321310, 2025). "Moreover, elevated SMPD2 expression was positively correlated with increased M2 macrophage infiltration, higher MMP12 expression, and poorer survival outcomes in melanoma patients, further validating and reinforcing the clinical relevance of our findings." (PMID 41321310, 2025).
multiple myeloma (2 papers, 2019 to 2022). "SMPD2 and SMPD4 overexpression also result in a worse PFS in this myeloma subgroup." (PMID 31756922, 2019).
COVID-19 (1 paper, 2023). A disease caused by infection with severe acute respiratory syndrome coronavirus 2. "The expression levels of Cer-metabolizing enzymes derived from SM, such as sphingomyelinases (SMPD2 and SMPD3), were found to be downregulated in COVID-19 severity." (PMID 37566018, 2023).
diabetic kidney disease (1 paper, 2023). Progressive kidney disorder caused by vascular damage to the glomerular capillaries, in patients with diabetes mellitus. "SMPD2 may be related to diabetic kidney disease, as lower SMPD2 expression levels and decreased ceramide synthesis have been observed in patients with this condition." (PMID 38012235, 2023).
lipidosis (1 paper, 2018). "Both, SMPD2, which is potentially responsible for lipidosis (a lipid storage disorder in mammals), and CERS2, which encodes a protein associated with cancer growth suppression and involved in sphingolipid synthesis, were increased in expression during the photostimulated M state." (PMID 30538637, 2018).
ovarian carcinoma (1 paper, 2021). A malignant neoplasm originating from the surface ovarian epithelium. "Survival analysis showed that the high levels of SPHK1, KDSR, SMPD1, GALC, SMPD2, UGCG and DEGS1 were associated with poor prognosis of OS in patients with ovarian cancer, among which DEGS1 was the most significant (P = 3E-04)." (PMID 34488809, 2021).
tumor (21 papers, 1999 to 2025). "By focusing on crucial sphingolipid genes like SMPD2 and CSTA, the efficacy of anti-tumor therapy can be increased in HCC cells." (PMID 37006285, 2023). "By focusing on crucial sphingolipid genes, such as SMPD2 and CSTA, the sensitivity of HCC to anti-tumor therapy may be enhanced." (PMID 37006285, 2023).
cancer (14 papers, 2007 to 2025). A tumor composed of atypical neoplastic, often pleomorphic cells that invade other tissues. "CYLD and SMPD2 were characteristics of G2 cancer, and TNFR1, TNFR2, NFKB1, TAB2, and USP4 for G3 cancer." (PMID 37233761, 2023). "Here, the authors solve the structure of human neutral sphingomyelinase SMPD2 and propose a catalytic mechanism, potentially enhancing understanding of ceramide in disease and cancer treatment." (PMID 38012235, 2023). "SMPD2 inhibition with GW4869 has been shown to decrease exosome production while increasing ectosome production in cancer cell lines." (PMID 34773385, 2022). "The six main genes are involved in the cancer and inflammatory processes (YWHAZ, CCL2 and SMPD2) and lipid droplet formation and metabolism (CIDEC, VLDLR and FASN) and significantly increased in NASH patients compared to control or NAFL groups." (PMID 31717414, 2019).
SMPD2 also shares sentences with these, for which no sentence is quoted: glioma (7 papers); Cerebral ischemia (5); infection (5); hepatocellular carcinoma (4); diabetes (3); leukemia (3); microcephaly (3); myocardial infarction (3); atherosclerosis (2); dwarfism (2); dyslipidemia (2); emphysema (2); Hypertension (2); insulinoma (2); lymphoma (2); neurodegenerative disease (2); Obesity (2); Parkinson disease (2); prostate carcinoma (2); acute coronary syndrome (1); adenoma (1); alcohol abuse (1); Alzheimer disease (1); anemia (1); Anxiety (1); brain disorder (1); breast adenocarcinoma (1); Cachexia (1); cardiac ischemia (1); chronic heart failure (1).
A further 28 diseases each share a sentence with SMPD2 in 1 paper.